CRP (C-reactive protein)
Diseases named in the same sentence as CRP in open-access papers (continued):
Sharing a sentence is not in itself a finding about the gene and the disease.
Hypertension (continued). "In another cross-sectional study of 441 patients with T2DM, C-reactive protein (CRP) was associated with increased carotid IMT in patients with hypertension, and diabetic retinopathy was the only chronic microvascular complication independently associated with advanced carotid atherosclerosis." (PMID 41312353, 2025). "Association of smoking, hypertension, and C-reactive protein in the study population." (PMID 39347252, 2024). "Additionally, C-reactive protein, a potent inflammatory marker associated with hypertension risk, exhibits higher levels in hypertensive and prehypertensive patients compared to those with normal blood pressure." (PMID 38730326, 2024). "Increased hair cortisol concentrations (HCC) were in this study associated with various classical cardiovascular risk factors such as hypertension, high cholesterol, BMI and waist circumference (for women), type 2 diabetes, elevated fasting glucose, and high-sensitive CRP." (PMID 39367323, 2024). "Also, C-reactive protein (CRP) is associated with EC dysfunction and greater risk of CVD, with chronic elevations of CRP being associated with the development of hypertension." (PMID 39062880, 2024). "Our results indicated that older age and higher serum OC levels are associated with PAS in hypertensive patients; specifically, serum OC levels are positively associated with serum log-CRP levels and left or right baPWV values and negatively associated with eGFR in patients with hypertension." (PMID 38793018, 2024). "Moreover, CRP effects in this transgenic model are modulated by the genetic predisposition of SHR to the development of hypertension, where CRP can escalate future cardiovascular complications." (PMID 38627621, 2024). "Those with periodontitis or high CRP level had a higher risk of death, while the presence of periodontitis and high CRP level together increased the risk of death, particularly in older individuals and those with high blood pressure." (PMID 39453923, 2024). "The patient also had acute on chronic renal failure with hematuria, severe anemia, splenomegaly, paratracheal lymphadenomegaly, and arterial hypertension, associated with high levels of C-reactive protein (CRP), erythrocyte sedimentation rate (ESR), and rheumatoid factor (RF)." (PMID 37072873, 2023). "In this post hoc analysis of the MANCTRA-1 study, the association of age > 76 years, history of uncontrolled arterial hypertension, CRP > 125 mg/L, LDH > 510 U/L, renal failure, haemodynamic failure and acute cholangitis diagnosed within 72 h from hospital admission allowed to predict mortality." (PMID 36899292, 2023). "Finally, in a logistic regression model adjusted for age, sex, smoking status, hypertension, history of autoimmune disease and median CRP, CVID remained an independent risk factor for atherosclerotic CVDs (OR: 2.00, 95% CI: 0.90–4.40, p = 0.002)." (PMID 38028500, 2023). "In addition, omentin causes the dilation of blood vessels, helping to reduce the risk of arterial hypertension, and weakens angiogenesis induced by C-reactive protein." (PMID 37239168, 2023). "Additionally, many studies have demonstrated an association between hs-CRP and a range of diseases, such as hypertension, coronary artery disease, stroke, and cancer, which significantly contribute to death." (PMID 37095492, 2023). "Multiple clinical and epidemiologic studies have demonstrated that many plasma inflammatory markers such as C-reactive protein, high-sensitivity C-reactive protein, interleukin-6 and interleukin-1β are often elevated in patients with hypertension and associated with prognosis." (PMID 36817427, 2023). "The level of serum CRP in the healthy cohort is a risk factor for future essential hypertension." (PMID 36675499, 2023). "Several cross-sectional and cohort studies have reported an association between CRP and hypertension, and their studies all support the association between CRP and hypertension, and CRP may serve as a predictor of hypertension." (PMID 36418968, 2022).
Hypertension (continued). "We conducted a sensitivity analysis to investigate the association of elevated-CRP levels and untreated hypertension with new-onset stroke after excluding those with antihypertensive treatment; there was a robust combined effect of elevated-CRP levels and hypertension on stroke." (PMID 36262245, 2022). "The joint association of elevated-CRP levels and hypertension with new-onset stroke in CHARLS." (PMID 36262245, 2022). "Finally, adding the combination of elevated-CRP levels and hypertension to conventional factors significantly improved the risk prediction for new-onset stroke." (PMID 36262245, 2022). "Inflammatory factors such as c-reactive protein and interleukin-6 is increased with prolonged sleep duration, which can cause drowsiness and fatigue, and may also increase the risk of hypertension in people with long sleep duration." (PMID 35064191, 2022). "Therefore, we conducted a prospective study in 450 Chinese communities based on the China Health and Retirement Longitudinal Study (CHARLS) to examine the combined effects of elevated-CRP levels and hypertension on stroke risk." (PMID 36262245, 2022). "However, most of the study subjects included in their experiment were young and middle-aged men and women, so the experimental results suggest that CRP is independently associated with hypertension in younger age groups." (PMID 36418968, 2022). "Subsequently, scholars from home and abroad conducted cross-sectional and prospective studies on the association between CRP and hypertension, all of which confirmed that CRP was independently associated with hypertension and that CRP was one of the predictors of hypertension." (PMID 36418968, 2022). "Likewise, the Dietary Approaches to Stop Hypertension (DASH) diet has been reported to be associated with reduced concentrations of CRP." (PMID 36079748, 2022). "Hypertension is also linked to a pro-inflammatory state with studies demonstrating significant elevation of inflammatory markers such as interleukin-6 (IL-6) and c-reactive protein (CRP) in hypertensive subjects." (PMID 36126060, 2022). "In a study of the effect on the risk of hypertension in the US retired population, which included 2924 participants, logistic regression showed that CRP could be used as a predictor of hypertension in women." (PMID 36418968, 2022). "Ethnic group differences were evident in detecting the association of CRP levels with hypertension." (PMID 34314447, 2021). "Also, higher age, hypertension, smoking, hyperlipidemia, history of ischemic heart disease, heart and renal failure, and higher levels of c-reactive protein were significantly associated the presence of DEC." (PMID 34915852, 2021). "Among hypertensive individuals, CRP levels have been found to be positively associated with arterial stiffness and end-organ damage, and have been shown to predict future cardiovascular events and the rate of hypertension remission." (PMID 34943129, 2021). "Therefore, to adequately predict hypertension, CRP should be used in combination with other high-risk markers, especially baseline BP, age, WC, and TG." (PMID 34925916, 2021). "For example, C-reactive protein levels (found to be significantly elevated in this study by 93% in shift workers) are known to be significantly and independently associated with the future development of hypertension." (PMID 34948768, 2021). "After the adjustment of all the covariates (model 3), such as age, gender, BMI, educational level, hypertension, vitamin E, and CRP levels, serum 25(OH)D deficiency (OR: 1.770, 95% CI: 1.023-3.065, and P = 0.034) was still the independent risk factors for stroke." (PMID 34745384, 2021). "Therefore, the aim of our study was to explore the association between high sensitivity CRP (hs-CRP) levels and incident hypertension, as well as the association between CRP levels and related covariates, in a Chinese adult population." (PMID 34925916, 2021).
Hypertension (continued). "Based on survival analysis, the anti‐inflammatory treatment may be required in hypertension patients with high levels of CRP to reduce the death risk." (PMID 33112011, 2021). "Serum uric acid level is independently associated with CRP in the patient with hypertension." (PMID 34714968, 2021). "In addition, the same group of researchers, as well as others reported that CRP level was positively associated with systolic blood pressure, and hypertension." (PMID 33621259, 2021). "Logistic regression was used to analyze the risk of incident hypertension with hs-CRP." (PMID 34925916, 2021). "Is C-reactive protein an independent risk factor for essential hypertension?" (PMID 33909761, 2021). "Logistic regression identified the following variables which were also significant in univariate analysis as independent risk factors for death – increasing age, history of hypertension, current or previous cancer, admission CRP ≥100 μg/ml, admission platelet count <150 × 103/μl and AKI." (PMID 33228824, 2020). "These multiple-associated phenotype classes were associated with two (insulin/height, body mass index/C-reactive protein, smoking/myocardial infarction, hypertension/smoking) and three (smoking/LDL-C, hemoglobin/hematocrit, smoking/alcohol consumption) variants each." (PMID 31891604, 2019). "Moreover, several studies have reported an association between hypertension and elevated levels of C-reactive protein." (PMID 30167451, 2018). "The cytokine Interleukin-6 (IL-6) is a fundamental mediator of the acute-phase response to endothelial injury and regulates the production of C Reactive Protein (CRP) in hepatocytes; therefore, both IL-6 and CRP genetic variants have been evaluated in relation to hypertension." (PMID 29495593, 2018). "Moreover, MMP9 levels were affected by age and hypertension, and were positively associated with circulating CRP and Hcy." (PMID 30373522, 2018). "CRP levels were associated with hypertension in model 1 (P = 0.003)." (PMID 28837559, 2017). "After adjusting according to potential confounders, such as age, sex, and smoking, hypertension, type 2 DM, dyslipidemia, hcy, and CRP, CysC is an independent risk factor for large cerebral artery stenosis in patients with AIS (OR=17.46, 95 %CI 2.70−113.14, p=0.003)." (PMID 28978025, 2017). "Following multivariable adjustment (RA, presence of hypertension, age, sex, BMI, haemoglobin), hs‐CRP remained positively associated with HR (adjusted r2 = 0.375, P < 0.001), whereas the associations with MSNA burst frequency and cardiac BRS were no longer statistically significant." (PMID 27561790, 2017). "Elevated CRP levels have been associated with hypertension in pregnancy and with CVD." (PMID 28749442, 2017). "An increased CRP level is associated with several diseases, and a CRP level above 10 mg/L is associated with an increased risk of cardiovascular disease, rheumatoid arthritis, hypertension, and colorectal cancer." (PMID 27701463, 2016). "Similarly, patients with elevated hs-CRP showed higher risk for hypertension, hyperglycemia and low HDL cholesterol as compared to patients with non-elevated hs-CRP." (PMID 27006878, 2016). "In addition to the additional risk factors for CVD, such as age, hypertension, BMI, systolic pressure, CRP, UA, we found that ILD was also a specific risk factor for CVD among CTD patients." (PMID 25775471, 2015). "This association is explained by the adverse cardiovascular risk profile in obese individuals characterized by high blood pressure (BP), dyslipidaemia, hyperglycaemia, elevated level of C-reactive protein (CRP) and higher level of other biomarkers of cardiovascular risk." (PMID 25880559, 2015).
Hypertension (continued). "In the Colombian population, our group showed for the first time that high levels of CRP were associated with elevated blood pressure, leading to the hypothesis that low-grade inflammation is an independent risk factor for essential hypertension." (PMID 26491235, 2015). "CRP is considered the inflammatory marker with the strongest association with hypertension." (PMID 25136585, 2014). "A simple score constructed based on FPG, HbA1c, CRP as well as sex, BMI and hypertension could be used to screen and to estimate the risk for future T2DM in middle aged and older Chinese." (PMID 24819157, 2014). "These children do have high risk markers for high blood pressure, high cholesterol, high fasting glucose, high CRP and fasting insulin, all factors which cannot be easily measured but could be predicted from fitness tests." (PMID 25074589, 2014). "Moreover, we have demonstrated that in Andean women, CRP is an independent risk factor for pregnancy-induced hypertension and that in this population the concentration of CRP is increased in dyslipidemic subjects with MS as well as in overweight children." (PMID 23573414, 2013). "Finally CRP, the most investigated cytokine in hypertension, has been repeatedly implicated in both the initiation and progression of the disorder." (PMID 23152884, 2012). "Recent evidence indicates that high-sensitivity C-reactive protein (hs-CRP), an acute phase of an inflammatory marker, might be associated with atherosclerosis, hypertension, and other cardiovascular diseases." (PMID 22518282, 2012). "Additionally CRP (p<0.05), leptin (p<0.001) and leptin/adiponectin ratio (p<0.001) were also significantly associated with the hypertension phenotype." (PMID 23251471, 2012). "As has been shown in earlier studies, adjustment for cardiovascular risk factors resulted in a rather small reduction in the relative educational gradient in risk of future CVD, i.e. 8% for CRP and 21% for established risk factors taken together (current smoking, hypertension and hyperlipidemia)." (PMID 18518944, 2008). "In Models 1 and 2, which were adjusted for age alone and for age plus hypertension, respectively, higher Hs-CRP levels were already significantly associated with increased mortality risk, regardless of whether Hs-CRP was modeled as a continuous, log-transformed, or standardized variable." (PMID 41601759, 2026). "Higher diastolic blood pressure was positively associated with DR, suggesting a potential role of hypertension, while elevated CRP, an inflammatory marker, showed an inverse relationship with DR, indicating that inflammation may have complex effects in DR’s progression." (PMID 39992900, 2025). "CRP influences endothelial activation and dysfunction by modifying endothelial vasoreactivity, primarily through a reduction in endothelial nitric oxide synthase (eNOS) activity, which may heighten the risk of atherothrombosis, hypertension, and CAD." (PMID 39323757, 2024). "Considering that previous studies have suggested that the predictive power of CRP for adverse cardiovascular events may simply be due to its association with hyperglycemia, hypertension, and abnormal lipid metabolism, we adjusted for these factors in our final model." (PMID 39011047, 2024). "One of the possible reasons for these results is that physical activity in childhood and adolescence could reduce inflammatory parameters such as C-reactive protein, which would be linked to lower sympathetic activity and successively lower chances of having hypertension." (PMID 36802314, 2023). "Assuming that hypertension is a chronic inflammatory disease, organ complications may be associated not only with hemodynamic factors, but also with altered levels of inflammatory markers, e.g., CRP." (PMID 38203261, 2023).
Hypertension (continued). "In conclusion, our study results showed that the combined effect of elevated-CRP levels and hypertension can increase the risk of stroke among the middle-aged and geriatric Chinese population, and corresponding interventions may be worthwhile for stroke prevention." (PMID 36262245, 2022). "Additionally, targeted assessment and management of CumMHR, especially in participants at low diabetic risks defined by traditional risk factors (e.g., CRP, hypertension, overweight, smoking habits), are instrumental for further improvement of diabetic outcome." (PMID 36463212, 2022). "Furthermore, the current work demonstrates that the plasma level of miR-505 is positively correlated with SBP and the level of CRP in human subjects, lending addition support to the potential clinical implication of miR-505 in hypertension-associated inflammation." (PMID 35571179, 2022). "Cardiovascular risk factors associated with pediatric obesity include dyslipidemia, hypertension, insulin resistance, and the metabolic syndrome, as well as other non-traditional risk factors including increased levels of homocysteine, uric acid, and C-reactive protein." (PMID 33748038, 2021). "First, CRP may serve as a biomarker for predicting the risk of hypertension." (PMID 34925916, 2021). "Notably, even without adjusting for measures of adiposity, our results also show a weak positive association between hs-CRP levels and future incidence of hypertension, which is significantly lower than the strong positive association seen in Europe and the United States." (PMID 34925916, 2021). "To investigate whether the elevated CRP observed in our sample may be related to systemic conditions known to be associated with increased inflammation, we repeated our analyses, excluding individuals diagnosed with hypertension (n = 187) and CVD (n = 53)." (PMID 33807159, 2021). "Most previous studies have demonstrated a positive association between CRP levels and the risk of hypertension in different populations, which is consistent with our findings; however, not all studies have demonstrated that CRP predicts the occurrence of hypertension accurately." (PMID 34925916, 2021). "As the prevalence of hypertension and dyslipidemia continues to rise and cardiovascular diseases have come to be the second leading cause of deaths for Koreans in 2017, it is necessary to elucidate the various factors that affect expression and regulation of CRP." (PMID 31590321, 2019). "Other unmeasured risk factors, for instance, hypoadiponectinemia, C-reactive protein, anticipatory stress, and obstructive sleep apnoea syndrome, may play a role in the development of hypertension as well and may further explain these associations and interactions." (PMID 31316827, 2019). "There is growing evidence that low level of CRP is closely related to the risk factor of cardiovascular disease, such as hypertension and hyperlipidemia, and that the elevation of CRP level can increase the incidence of heart disease and stroke for patients with hypertension." (PMID 29739462, 2018). "Furthermore, although some prospective studies have shown associations between CRP and incident hypertension, others have shown these to disappear after adjustment for BMI, suggesting that BMI is a common determinant of both pulse pressure/hypertension and CRP." (PMID 29101422, 2018). "The study found that carrying the rs3746444 AA had a lower level of serum CRP compared to those rs3746444AG/GG, miR-499 would increase the concentration of serum or plasma C-reactive protein, causing increased risk factors for stroke, such as inflammation, hypertension, and hyperlipoidemia." (PMID 29113388, 2017). "Also increased CRP levels are one of the major causes of pre-hypertension, which may be considered as short-term risk for ischemic stroke." (PMID 26989902, 2016).